DOT1L (DOT1 like histone lysine methyltransferase)
Diseases named in the same sentence as DOT1L in open-access papers (continued):
Sharing a sentence is not in itself a finding about the gene and the disease.
lymph node metastasis (2 papers, 2017 to 2022). "High expression of DOT1L was associated with FIGO stage (P = 0.001), histologic grade (P = 0.012), and lymph node metastasis (P = 0.036)." (PMID 28114995, 2017). "Higher DOT1L expression was associated with advanced FIGO stage, poor histopathological grade, and lymph node metastasis of OC patients." (PMID 28114995, 2017).
metastatic disease (2 papers, 2016 to 2026). "Clinical LUAD specimens further validated the correlation between DOT1L expression, STAT3 activation, and checkpoint upregulation, particularly in metastatic disease." (PMID 41836439, 2026).
microcephaly (2 papers, 2019 to 2023). A congenital or acquired developmental disorder in which the circumference of the head is smaller than normal for the person's age and sex. "Moreover, DOT1L depletion as well as DOT1L mutations that alter its activity and abundance have been implicated in neurodevelopmental diseases including microcephaly, and different types of cancer." (PMID 37759327, 2023). "Histological characterization at P0 showed that Dot1l-cKO animals had microcephaly affecting ventral and dorsal structures." (PMID 30329130, 2019).
myeloid leukemia (2 papers, 2024). A clonal proliferation of myeloid cells and their precursors in the bone marrow, peripheral blood, and spleen. "Indeed, the pleiotropic gene set was found to have an overrepresentation of regulators of myeloid leukemia: DOT1L, EP300, FLI1, GSE1, and MED24 (OR = 7.1; phypergeometric = 4 × 10−4)." (PMID 38308367, 2024).
Obesity (2 papers, 2020 to 2024). Accumulation of substantial excess body fat. "In this regard, the GWAS database reveals multiple SNPs of Dot1l associated with a waist-hip ratio and body mass index, further supporting a potential role of Dot1l in human obesity (GWAS Central identifier: HGVPM1111, HGVPM1114)." (PMID 33107819, 2020). "It will therefore be of great interest to understand how inhibition of DOT1L affects the onset and maintenance of inflammatory processes during obesity." (PMID 38962004, 2024). "In particular, its role in fat mast cells, where DOT1L is highest expressed in the immune system, could shed a new light on epigenetic regulations in the pathophysiology of obesity." (PMID 38962004, 2024). "Hence, Dot1l plays a critical role in the thermogenic program and may present as a future target for obesity therapeutics." (PMID 33107819, 2020). "Interestingly, DOT1L is a regulator of thermogenic adipocyte differentiation and function, and is thereby a key epigenetic modifier in obesity, showing that DOT1L may pose a highly interesting target (e.g. by stabilising its activity or by providing sufficient substrate) in obesity." (PMID 38962004, 2024).
Peritoneal Fibrosis (2 papers, 2024). Disorder characterized by a wide range of structural changes in PERITONEUM, resulting from fibrogenic or inflammatory processes. "The disruptor of telomeric silencing 1-like (DOT1L), a specific histone methyltransferase that catalyzed methylation of histone H3 on lysine 79, was associated with the pathogenesis of many diseases, but its role in peritoneal fibrosis remained unexplored." (PMID 38172378, 2024). "Therefore, targeting DOT1L may offer new opportunities for clinical drug development against dialysis-associated peritoneal fibrosis." (PMID 39749340, 2024). "Here, we examined the role of DOT1L in the expression and activation of protein tyrosine kinases and development of peritoneal fibrosis." (PMID 38172378, 2024). "Inhibition of DOT1L significantly attenuated the profibrotic phenotypic differentiation of mesothelial cells and macrophages, and alleviated peritoneal fibrosis." (PMID 38172378, 2024). "In summary, the current study uncovered a new role for DOT1L in modulating the pathophysiology of peritoneal fibrosis." (PMID 38172378, 2024). "Inhibiting DOT1L can effectively reduce the transdifferentiation of mesothelial cells and phenotypic differentiation of macrophages into M2 macrophages, thereby alleviating peritoneal fibrosis." (PMID 39749340, 2024). "Targeting DOT1L pharmacologically could potentially offer a promising therapeutic strategy for mitigating peritoneal fibrosis and improving peritoneal functions in patients undergoing PD." (PMID 38172378, 2024). "Pharmacological inhibition of DOT1L by EPZ5676 can block these processes and attenuate the peritoneal fibrosis." (PMID 38172378, 2024). "In conclusion, DOT1L promotes the expression and activation of tyrosine kinases, specifically EGFR in mesothelial cells and JAK3 in macrophages, driving cell differentiation towards a pro-fibrotic phenotype, ultimately leading to peritoneal fibrosis." (PMID 39749340, 2024). "In summary, DOT1L promoted the expression and activation of tyrosine kinases (EGFR in mesothelial cells and JAK3 in macrophages), promoting cells differentiate into profibrotic phenotype and thus peritoneal fibrosis." (PMID 38172378, 2024). "DOT1L proceeds mesenchymal phenotype differentiation of MCs through upregulating and activating EGFR, and facilitates M2 differentiation of macrophages by upregulating and activating JAK3, subsequently promoting the deposition of ECM and subsequent peritoneal fibrosis." (PMID 38172378, 2024). "However, whether DOT1L is responsible for peritoneal fibrosis has not been elucidated." (PMID 38172378, 2024).
pulmonary fibrosis (2 papers, 2022 to 2026). Chronic progressive interstitial lung disorder characterized by the replacement of the lung tissue by connective tissue, leading to progressive dyspnea, respiratory failure, or right heart failure. "Furthermore, heterozygous DOT1L-deficient mice (Dot1l+/−) showed less sensitive to pulmonary fibrosis, as shown by decreased lung fibrosis phenotypes in vivo." (PMID 35039472, 2022). "Collectively, these findings establish DOT1L as a critical epigenetic driver of EndoMT and pulmonary fibrosis through H3K79me2-mediated transcriptional activation, highlighting it as a potential therapeutic target in fibrotic lung disease." (PMID 41933932, 2026). "As expected, the protein expression levels of FN, MMP9/2, CTGF, and Collagen I also decreased by Dot1l shRNA in lung fibrosis process." (PMID 35039472, 2022). "To further unravel the role of DOT1L in bleomycin-induced mouse pulmonary fibrosis in vivo, we newly constructed the heterozygous DOT1L-deficient mice (Dot1l+/−)." (PMID 35039472, 2022). "Of note, DOT1L depletion in vivo markedly inhibited the protein expression levels of bleomycin-induced pulmonary fibrosis markers (FN, CTGF, α-SMA, Collagen I/III, and MMP2/9)." (PMID 35039472, 2022). "To investigate the role of DOT1L in pulmonary fibrosis, we constructed the widely used mouse pulmonary fibrosis model by intratracheal administration of bleomycin." (PMID 35039472, 2022). "Dot1l+/− mice as well as intervention with the DOT1L small-molecular inhibitor EP5676 blunted the pulmonary fibrosis phenotypes including the collagen deposition and increased pulmonary fibrosis marker expression levels." (PMID 35039472, 2022). "Lentivirus-mediated DOT1L knockdown or DOT1L-specific inhibitor EPZ5676 alleviated the pathogenesis of bleomycin-induced mouse pulmonary fibrosis." (PMID 35039472, 2022). "Further exploring with the specific inhibitor EPZ5676 or Dot1l shRNA demonstrated that DOT1L disruption inhibited bleomycin-induced mouse pulmonary fibrosis in vivo, as indicated by decreased collagen deposition and pulmonary fibrosis marker expression levels." (PMID 35039472, 2022). "Collectively, these data demonstrate that histone methyltransferase DOT1L is a novel epigenetic driver in pulmonary fibrosis, while blockade of DOT1L effectively decreases the pulmonary fibrosis phenotypes." (PMID 35039472, 2022). "Dot1l+/− mice showed normal growth under physiological conditions but showed less sensitive to the progression of pulmonary fibrosis." (PMID 35039472, 2022). "DOT1L, H3K79me3, and the profibrotic proteins levels were upregulated in the pulmonary fibrosis models both in vivo and in vitro." (PMID 35039472, 2022). "In this study, we discovered the direct participation of DOT1L in regulating the pulmonary fibrosis phenotypes, contributing to the development of IPF via Jagged1-Notch signaling." (PMID 35039472, 2022). "Blockade of DOT1L preserves pulmonary fibrosis by preventing the hyper-activation of Jagged1-Notch signaling." (PMID 35039472, 2022). "Knockdown or pharmacological inhibition of DOT1L could block TGF-β1-induced upregulation in the protein levels of lung fibrosis markers, such as CTGF, FN, and MMP9." (PMID 35039472, 2022). "Our study identifies DOT1L as a epigenetic regulator of lung fibrosis." (PMID 35039472, 2022). "Interestingly, severe pulmonary fibrosis was shown in bleomycin-administrated WT mice for 14 days but was attenuated in Dot1l+/− mice, as determined by H&E staining as well as the Szapiel score." (PMID 35039472, 2022). "Pharmacological targeting of DOT1L might represent a promising therapeutic approach for human pulmonary fibrosis and other fibrotic diseases." (PMID 35039472, 2022). "Interestingly, in our present study, we found DOT1L is upregulated in pulmonary fibrosis models both in vivo and in vitro, revealing a potential indication for its role in pulmonary fibrosis progression." (PMID 35039472, 2022).
pulmonary fibrosis (continued). "However, whether DOT1L is responsible for pulmonary fibrosis has yet to be fully elucidated, and DOT1L-based approaches may be critical for discovering novel anti-fibrotic therapies, therefore improving clinical outcomes for IPF patients." (PMID 35039472, 2022). "On this basis, the present study discloses a novel role of DOT1L in regulating the pathophysiology of pulmonary fibrosis and inhibition of DOT1L may represent an effective approach to improve the lung functions in the pulmonary fibrosis." (PMID 35039472, 2022). "Furthermore, mice treated with EPZ5676 or Dot1l shRNA presented lower Ashcroft histopathological grading score and hydroxyproline contents, which were used as the semi-quantitative methods to evaluate the severity of pulmonary fibrosis." (PMID 35039472, 2022). "Interestingly, DOT1L was also upregulated during pulmonary fibrosis." (PMID 35039472, 2022). "Consistent with the elevated expression of DOT1L, the abundance of trimethylation of H3K79 (H3K79me3) in the lung fibrosis also increased relative to total histone H3 levels." (PMID 35039472, 2022). "Similarly, both DOT1L and alpha-smooth muscle actin (α-SMA) showed significantly increased expression levels in bleomycin-induced lung fibrosis, as detected by immunohistochemical staining." (PMID 35039472, 2022). "However, the relationship between DOT1L and Notch signaling in lung fibrosis has not been explored." (PMID 35039472, 2022).
retinoblastoma (2 papers, 2021 to 2024). A malignant tumor that originates in the nuclear layer of the retina. "Therefore, targeting epigenetic dysregulation, particularly through DOT1L inhibition, holds promise for advancing the treatment of retinoblastoma and minimizing the long-term adverse effects associated with conventional chemotherapy." (PMID 38672640, 2024). "While DOT1L was found to be expressed in most human retinoblastoma cases, its expression was undetectable in normal retina, suggesting a potential selective vulnerability for DOT1L targeting in retinoblastoma cells." (PMID 38672640, 2024). "Indeed, DOT1L inhibition sensitized retinoblastoma cells to etoposide-induced apoptosis, enhancing the therapeutic effects of DNA-damaging agents." (PMID 38672640, 2024). "Since HMGA2 promotes retinoblastoma cell proliferation and regulates DNA damage response, these findings suggest that DOT1L inhibition plays a dual role in chemosensitizing retinoblastoma cells by impairing early DNA damage response and downregulating HMGA2 expression." (PMID 38672640, 2024). "Additionally, the non-histone chromosome protein HMGA2 was identified as a novel target gene of DOT1L in retinoblastoma cells, with its expression epigenetically upregulated by DOT1L." (PMID 38672640, 2024).
thymic lymphoma (2 papers, 2019 to 2022). "To further study the Dot1L dependence of Hdac1‐deficient thymic lymphomas in a more controlled environment, we turned to ex vivo experiments." (PMID 31304633, 2019). "This regulation is relevant in a cancer context, since heterozygous deletion of Dot1L prolongs the survival of mice that develop Hdac1‐deficient thymic lymphomas." (PMID 31304633, 2019). "Cell lines derived from Hdac1‐deficient thymic lymphomas undergo apoptosis upon DOT1L inhibition or depletion, which indicates a form of non‐oncogene addiction to DOT1L." (PMID 31304633, 2019). "Thus, shRNA‐mediated DOT1L knockdown and chemical DOT1L inhibition showed that the Hdac1‐deficient thymic lymphoma cell lines depended on DOT1L activity." (PMID 31304633, 2019). "Thus, DOT1L inhibition induced apoptosis specifically in Hdac1‐deficient thymic lymphoma cell lines." (PMID 31304633, 2019). "Mice with conditional Hdac1 alleles but wild type for Dot1L (Lck‐Cre;Hdac1f/f) developed thymic lymphomas for which they had to be sacrificed, with a median latency of 21 weeks and an incidence of 86% during the 40‐week length of the experiment, comparable to what was observed before." (PMID 31304633, 2019). "In the mouse, thymic lymphoma cell lines derived from conditional Hdac1 knock-out mice also show increased H3K79me and this coincides with increased sensitivity towards DOT1L inhibitors." (PMID 36425063, 2022). "In summary, we identified an evolutionarily conserved crosstalk between HDAC1 and DOT1L with impact in murine thymic lymphoma development." (PMID 31304633, 2019). "Heterozygous Dot1L deletion prolonged the survival of mice with thymocyte‐specific Hdac1 deletion due to a lower incidence and increased latency of thymic lymphomas." (PMID 31304633, 2019). "HDAC1 negatively regulates DOT1L activity in yeast, mouse thymocytes, and mouse thymic lymphoma." (PMID 36425063, 2022). "Also, Dot1L deletion alone (Lck‐Cre;Dot1Lf/f) rarely led to thymic lymphomas, with a 15% incidence in this background, and no cases of thymic lymphoma in another background (data not shown)." (PMID 31304633, 2019). "Furthermore, cell lines derived from Hdac1Δ/Δ thymic lymphomas were sensitive to a DOT1L inhibitor, which induced apoptosis." (PMID 31304633, 2019). "Interestingly, homozygous Dot1L deletion, leading to a complete loss of H3K79me, did not extend the latency of thymic lymphomas (81% incidence, 15.7‐week median latency, comparison to Hdac1 deletion alone P = 0.463)." (PMID 31304633, 2019).
acute promyelocytic leukemia (1 paper, 2022). An aggressive form of acute myeloid leukemia (AML), characterized by arrest of leukocyte differentiation at the promyelocyte stage, due to a specific chromosomal translocation t(15;17) in myeloid cells. "Diseases associated with DOT1L include NUT midline carcinoma and acute promyelocytic leukemia." (PMID 36585729, 2022).
allergic reactions (1 paper, 2024). "These targeted deliveries would possibly allow for great success in precision medicine, e.g. the targeting of DOT1L in Th2 cells for the treatment of allergic reactions, as suggested earlier." (PMID 38962004, 2024).
autism (1 paper, 2019). Persistent deficits in social interaction and communication and interaction as well as a markedly restricted repertoire of activity and interest as well as repetitive patterns of behavior. "Cadps2 was a DOT1L-dependent gene and its expression levels need to be tightly controlled, as imbalanced levels are associated with neurological diseases such as autism." (PMID 30302725, 2019).
bladder cancer (1 paper, 2017). "PKMTs like DOT1L, SMYD2, JMJD2C have been reported in other cancers, but information on PKMTs are generally lacking in bladder cancer." (PMID 28122346, 2017).
brain hemorrhage (1 paper, 2024). "Our analysis revealed that DOT1L is broadly expressed in various organs of adult mice, and its loss results in brain hemorrhage and increased vascular permeability." (PMID 38665093, 2024). "In a mouse model of Rosa26-creER-mediated inducible Dot1l knockout, we observed vascular phenotypes, including increased vascular permeability and brain hemorrhage, when DOT1L was deleted in adulthood." (PMID 38665093, 2024).
cardiac interstitial fibrosis (1 paper, 2022). "Further, we provided evidence that in mice with either systolic or diastolic dysfunction, higher level of Dot1L showed high commonality in severe cardiac interstitial fibrosis." (PMID 35986422, 2022). "EPZ5676, a Dot1L specific inhibitor, treatment for 2 weeks post-MI alleviated cardiac interstitial fibrosis and the MI-induced increase in LV mass." (PMID 35986422, 2022).
cardiomyopathy (1 paper, 2025). A disease of the heart muscle or myocardium proper. "The cardiomyopathy-associated targets were Dnmt1, Hdac1, Dot1l, Setd5, Nsd2, Usp3, Bap1, Prkca, Prkcb, Crebbp and Clock: 11 out of 81 (13.6% of total targets)." (PMID 40076868, 2025).
cervical tumour (1 paper, 2024). "2HB has been reported to promote cervical tumour cell survival via stimulation of the methyltransferase DOT1L." (PMID 39226092, 2024).
chronic obstructive pulmonary disease (1 paper, 2024). A chronic and progressive lung disorder characterized by the loss of elasticity of the bronchial tree and the air sacs, destruction of the air sacs wall, thickening of the bronchial wall, and mucous accumulation in the bronchial tree. "Additionally, in patients suffering from chronic obstructive pulmonary disease (COPD), a notable downregulation of the histone methyltransferase DOT1L has been observed in the vastus lateralis muscle." (PMID 38978023, 2024).
colorectal mucinous adenocarcinoma (1 paper, 2019). An invasive colorectal adenocarcinoma characterized by the presence of extracellular mucin pools that contain malignant glandular epithelial structures. "Interestingly, DOT1L expression in colorectal mucinous adenocarcinoma is the highest among several different types of CRCs, such as COAD, READ, and rectosigmoid adenocarcinoma." (PMID 31888761, 2019).
embryonic carcinoma (1 paper, 2023). "We detected the H3K79me2 in Dot1l depletion-F9 cells (mouse embryonic carcinoma cell)." (PMID 38093377, 2023).
endolymphatic hydrops (1 paper, 2023). An accumulation of endolymph in the inner ear (labyrinth) leading to buildup of pressure and distortion of intralabyrinthine structures, such as cochlea and semicircular canals. "Dot1l in guinea pig cochlea is inhibited by aldosterone with induction of endolymphatic hydrops." (PMID 36639782, 2023).
folate deficiency (1 paper, 2023). A nutritional condition produced by a deficiency of FOLIC ACID in the diet. "Together, our results provide evidence that folate deficiency affects DOT1L activity and the levels of H3K79me2, which is related to abnormal expression of SHH, SUFU genes and subsequently NTDs." (PMID 38093377, 2023).
graft versus host disease (1 paper, 2018). An immune system disorder that occurs after allogeneic hematopoietic stem cell transplant and is a reaction of donor immune cells against host tissues. "The inhibition of DOT1L or DUSP6 overexpression in T cells attenuates the development of graft-versus-host disease, while retaining potent antitumor activity in xenogeneic and allogeneic adoptive immunotherapy models." (PMID 29765028, 2018).
gynecologic cancers (1 paper, 2022). "Two recent studies pointed to DOT1L as a promising target for gynecological cancer (GC) treatment." (PMID 35495127, 2022).